BRAF (B-Raf proto-oncogene, serine/threonine kinase)
Diseases named in the same sentence as BRAF in open-access papers (continued):
Sharing a sentence is not in itself a finding about the gene and the disease.
melanoma (continued). "The advent of BRAF and MEK inhibitors used in combination has become a standard therapeutic approach in patients with BRAF-mutated melanoma." (PMID 29423085, 2018). "Immunoprecipitation of BRAF from Mel-Juso human melanoma cell lysate resulted in the isolation of a strong ~85 kDa band on a Coomassie-stained gel near the area of an immunoreactive Western blot band from an identically-loaded gel lane." (PMID 29481571, 2018). "In this particular case, we suggest incorporating the NRAS mutation status, but omitting the BRAF mutation status, in fitting NLME curves for Topotecan in melanoma cell lines." (PMID 29435161, 2018). "The melanoma cells are classified as either sensitive (n = 3) or resistant (n = 2) based on the IC50 values for the BRAF/MEK inhibitors as determined by a viability assay." (PMID 29541007, 2018). "Targeted treatment of activated oncogenes is mainly directed against mutant BRAF (present in 40–50% of all melanomas) using the small molecule inhibitors vemurafenib, dabrafenib and encorafenib." (PMID 29614062, 2018). "Other types of siRNAs that regulate transposon expression were also shown to be differentially expressed in these datasets, suggesting the possibility that transposon-derived transcripts are altered in these BRAF inhibitor resistant melanoma cells." (PMID 30349559, 2018). "In melanoma, 48–59% of tumors harboring the BRAFV600E mutation show a clinical response to BRAF inhibition." (PMID 29192388, 2018). "The major effect was found in the association between Ole and Everolimus (RAD001), also on PLX4032-resistant BRAF melanoma cells, which possibly cooperate in the inhibition of the pAKT/pS6 pathway." (PMID 30544808, 2018). "Melanomas harboring constitutively active BRAF protein, or about half of all melanoma cases, showed low levels of PGC1α due to BRAF suppression of the melanocyte lineage factor, MITF, which directly regulates PGC1α." (PMID 29361779, 2018). "This is supported by in vivo human data showing that BRAF-mutant melanoma tumours with AKT signalling pre-treatment can undergo substantial tumour shrinkage in response to combination BRAF/MEK inhibition." (PMID 30237495, 2018). "~60% of melanomas express the constitutively active BRAF (BRAFCA) and are sensitive to inhibition by BRAFCA-specific inhibitors." (PMID 29450192, 2018). "In this phase III clinical trial, the combined therapy with binimetinib plus encorafenib improved PFS and objective response rate by local and central review when compared with vemurafenib in BRAF mutant melanoma patients." (PMID 29455659, 2018). "We have tested the ability of TEsmall to characterize the expression profiles of sRNAs from a variety of classes in the context of melanoma cell lines responding to targeted inhibitors of the BRAF oncogene." (PMID 30349559, 2018). "The majority of patients with metastatic BRAFV600E/K-mutant melanoma will fail BRAF inhibitor-based targeted therapy within the first year of treatment." (PMID 30237495, 2018). "The existence of FGFR1 expression prior to BRAF inhibition allows the melanoma cells to react immediately on the drug-induced ligands without the need for selection." (PMID 30237393, 2018). "In 50–75% of melanomas progressing on BRAF inhibitor or combination BRAF/MEK inhibition, common resistance effectors, including BRAF copy number gains, MEK1/2 and NRAS mutations promote the reactivation of MAPK signalling." (PMID 30237495, 2018). "Knockdown of c-Jun resulted in decreased levels of PD-L1 in melanoma cells resistant to BRAF inhibitors, and co-activation of STAT3 and the subsequent formation of a transcriptional complex further enhanced these effects." (PMID 29765155, 2018).
melanoma (continued). "The inhibitors of mutated BRAF, vemurafenib, and dabrafenib, made a breakthrough in the treatment of BRAF-driven melanomas, especially when given in combination with MEK inhibitors." (PMID 30211169, 2018). "At this time, two BRAF inhibitors have been FDA‐approved for the treatment of advanced (stage IV) unresectable melanoma." (PMID 29112787, 2018). "Here, we show in several melanoma cell lines that BRAF inhibition induces a secretome with stimulating effect on fibroblasts and naive melanoma cells." (PMID 30237393, 2018). "Mechanistically, it has been shown in BRAF V600E mutant colorectal cancer and melanoma cell lines that overactivation of the MAPK pathway phosphorylates and upregulates MAFG which functions as a transcriptional repressor." (PMID 30598662, 2018). "Both pharmacologic inhibition of mitogen-activated protein kinase (MEK) and small interfering RNA (siRNA) knockdown of ERK1/2 resulted in decreased levels of PD-L1 in melanoma cells resistant to BRAF inhibition." (PMID 29765155, 2018). "BRAF inhibitor resistance of melanoma can be a consequence of bypassing MAPK signaling via the PI3K-Akt pathway." (PMID 30360441, 2018). "Novel targeted and immunotherapeutic agents have also revolutionized the systemic management of melanoma (ipilimumab, nivolumab, pembrolizumab, and BRAF inhibitors dabrafenib and vemurafenib)." (PMID 29881714, 2018). "YAP/TAZ-dependent actin cytoskeleton remodeling and cell spreading promote an acquisition of a phenotype resistant against the treatment with the BRAF inhibitor PLX4032 (vemurafenib) in melanoma cells in vitro." (PMID 30101371, 2018). "E2F1 inhibition decreased the viability of melanoma cells with acquired resistance to BRAF inhibitor through the induction of apoptosis and DNA damage." (PMID 29743521, 2018). "But even in BRAFV600E/K melanoma cells responding to BRAF inhibition, the anti-tumorigenic effect is limited, as apoptosis induction is incomplete." (PMID 30237393, 2018). "These driver mutations are almost always mutually exclusive, making it possible to classify melanoma cases in distinct genomic subtypes: BRAF, RAS, NF1, and Triple-WT, the latter being defined by the absence of BRAF, RAS, and NF1 mutations." (PMID 30166456, 2018). "Yet significant improvements have expanded the therapeutic options for treating brain metastases from melanoma, by combining potent BRAF inhibitors such as dabrafenib with checkpoint inhibitors or stereotactic surgery." (PMID 30053879, 2018). "SOX10 expression was depleted using two independent SOX10-specific siRNAs in mutant BRAF melanoma cells which were then treated with the RAF inhibitor, Vemurafenib, for various times." (PMID 29295999, 2018). "A prominent example of resistance driven by re-activation of downstream signalling is through paradoxical activation of the MAPK (mitogen-activated protein kinase) pathway in BRAF V600E mutant melanoma." (PMID 30072489, 2018). "Current drug treatments for BRAFV6ooE-positive melanoma focus on administering inhibitors for BRAF and Mek1/2 but as with many other drugs, subsets of melanomas develop resistance." (PMID 33912613, 2018). "On the other hand, treatment of BRAF-mutant melanoma patients with BRAF inhibitors in monotherapy or in combination with MEK inhibitors is limited by both acquired and intrinsic drug resistance." (PMID 30290811, 2018). "BRAF inhibitors, which are accepted as standard treatment for V600E mutant malign melanomas, are the newest approach for targeted treatment of V600E mutant colorectal cancers." (PMID 29850361, 2018). "One unexpected off‐target effect of vemurafenib was the rapid development of cutaneous lesions including squamous cell carcinomas (SCC) (frequently of the rare keratoacanthoma type), actinic keratoses, and secondary (non‐BRAF‐mutant) melanomas." (PMID 29112787, 2018).
melanoma (continued). "The consensus was that patients with BRAF wild-type melanoma should receive immunotherapy in the adjuvant setting, BRAF-mutant patients should be offered both options: PD1-blockade as well as dabrafenib and trametinib." (PMID 30595751, 2018). "Despite these therapeutic successes, melanoma cells acquire the ability to withstand combined BRAF and MEK inhibition." (PMID 30558661, 2018). "Our data clearly indicate that E2F1 inhibition potentiates the anti-proliferative and pro-apoptotic effects of BRAF inhibitors, PLX4032 and dabrafenib, in melanoma cell lines sensitive to BRAF inhibitor." (PMID 29743521, 2018). "And the analysis of recurrent melanomas allowed the identification of novel candidates responsible for the resistance to the BRAF inhibitor PLX4720, with strong potential implications into the human clinics." (PMID 29534457, 2018). "A further 20% of BRAF inhibitor resistant melanomas acquire alterations that stimulate both the MAPK cascade and the compensatory PI3K/AKT survival network." (PMID 30237495, 2018). "The rationale for this is that the retinoblastoma protein (pRb) is 95% wildtype in BRAF mutant melanoma." (PMID 29541385, 2018). "It is thus anticipated that both combination therapies with BRAF/MEK inhibitors and checkpoint inhibitors will be approved in patients who have had high-risk melanomas resected." (PMID 29946532, 2018). "We investigated ribociclib 250 mg/kg and a lower, more clinically relevant dose (75 mg/kg) both alone and in combination with 5 mg/kg of encorafenib in the patient-derived melanoma model HMEX1906 (BRAF V600E)." (PMID 30443290, 2018). "MHC class I molecules (HLA-ABC) were uniformly expressed on melanoma cells with the exception of the BRAF/NRASWT SMU15-0217 (relative MFI = 1.5) and the uveal MP46 cells (relative MFI = 2.3)." (PMID 29977240, 2018). "In the present study, we demonstrate that rMETase is effective against a BRAF-V600E-negative melanoma PDOX which we established." (PMID 29416666, 2018). "Mutations in BRAF gene were initially identified in cancer types that are commonly associated with mutations in different isoforms of RAS, such as malignant melanoma and well-differentiated thyroid cancer." (PMID 29504908, 2018). "Alterations in BRAF, NRAS, and NF1 define the canonical genetic subtypes of melanoma, yet each of these oncogenic mutations is insufficient to drive tumorigenesis." (PMID 29875996, 2018). "Twelve of the 33 wild-type BRAF melanoma patients (36.4%) had at least 2 lines of treatment, and all except two received ipilimumab before anti-PD-1 administration (n = 31, 93.9%)." (PMID 29970025, 2018). "The combination of BRAF inhibition with systemic immunotherapy is therefore an appealing therapeutic approach in the treatment of patients with advanced melanoma." (PMID 30053905, 2018). "In this study, we investigated the precise contribution of PI3K/AKT signalling in melanoma resistance to BRAF/MEK inhibition." (PMID 30237495, 2018). "To investigate the molecular consequences of BRAFi-recruitment on AhR, we established the transcriptomes of BRAF-V600E melanoma cells (501Mel) exposed to Vem and to TCDD." (PMID 30429474, 2018). "Next, we analyzed the levels of secreted SPINK1 and its putative serine protease targets trypsin‐1 and trypsin‐2 in a panel of CRC and melanoma cell lines harboring either wild‐type or V600E BRAF." (PMID 29193645, 2018). "Conversely, another study showed that in mice inactivation of FOXO4 results in senescence bypass and consequently restores oncogenic‐BRAF induced melanoma formation." (PMID 29683489, 2018). "The other two histone methyltransferases (HMTs), SETDB1 and Histone-lysine N-methyltransferase SUV39H1 (SUV39H1), also cooperate with BRAF V600E to accelerate the incidence and severity of melanoma development in fish." (PMID 30544544, 2018).
melanoma (continued). "A recently published retrospective analysis and a prospective study of 25 melanoma patients support the experimental data and showed response after re-challenge with a BRAF inhibitor." (PMID 30344946, 2018). "PTPIP51/BRAF interaction is lowest in dysplastic nevi melanocytes, and somewhat higher in melanoma cells and highest in healthy melanocytes, where the number of interactions was five times higher compared to that of dysplastic nevi cells." (PMID 30360441, 2018). "For example, BRAF-KDD was identified as a new mechanism of drug resistance in patients with melanoma after BRAF inhibitor treatment." (PMID 29455648, 2018). "Most studies have focused on malignant melanoma and to some extent colorectal cancers, but little is known about the importance of circulating BRAF DNA in other cancers and how this information is related to BRAFi combination therapy." (PMID 30220966, 2018). "Cross-correlation of USP28 expression in BRAF (V600E) melanoma patients indicated that in this subset of patients, once again low levels of USP28 conferred lower overall survival." (PMID 29880484, 2018). "We were initially interested in characterizing binding partners of the 85 kDa isoform of BRAF in human melanoma cells detected by different anti-BRAF antibodies." (PMID 29481571, 2018). "Incorporation of FAK, Src or PDGFR inhibitors re-sensitized melanoma cells towards BRAF inhibitor in the co-culture system of tumour and stromal cells via re-activation of ERK." (PMID 29455663, 2018). "We have shown that sustained lipogenesis through the maintenance of active SREBP-1 is a key feature of therapy resistance to vemurafenib in BRAF-mutant melanoma, and that inhibition of SREBP-1 sensitizes melanoma to targeted therapy." (PMID 29950559, 2018). "The essentiality of BRAF and its co‐functional gene partners paints a similar picture, primarily with respect to melanoma cell lines." (PMID 30573688, 2018). "Clinically, vemurafenib has demonstrated efficacy in treating BRAF-mutant melanoma patients, eventually received Food and Drug Administration (FDA) approval in 2011 for the treatment of late-stage melanoma." (PMID 29765977, 2018). "We have also demonstrated that CD271 is a characteristic marker of IDTCs in a BRAF mt melanoma model." (PMID 29492189, 2018). "But if an anti-BRAF therapy proves effective against melanoma, should we expect that effectiveness to carry over to patients with BRAF mutations in other cancers in which BRAF mutations are found at much lower frequencies?" (PMID 29854275, 2018). "Published phosphoproteomic studies have found that melanoma cells with acquired resistance to BRAF inhibitors display elevated levels of phosphoproteins that function in cytoskeletal regulatory pathways." (PMID 28842319, 2018). "Here, we report that RIP1 was upregulated and contributed to both intrinsic and acquired resistance of melanoma cells to BRAF/MEK inhibitors through activation of NF-κB." (PMID 29880840, 2018). "Similar to cutaneous melanomas, conjunctival melanomas can be grouped genetically into four groups: BRAF-mutated, RAS-mutated, NF1-mutated and triple wild-type melanomas." (PMID 29559732, 2018). "Here we show that SOX10 is both necessary and sufficient for RAF inhibitor-induced expression of FOXD3 in mutant BRAF melanoma cells." (PMID 29295999, 2018). "Mutations in the v-Raf murine sarcoma viral oncogene homolog B1 (BRAF) and neuroblastoma rat sarcoma viral oncogene homolog (NRAS) are found in 70–80% of all melanomas." (PMID 30026510, 2018). "For example, treatment of mutant BRAF melanoma cells with the BRAF inhibitor vemurafenib results in increased mitochondrial respiration." (PMID 30456204, 2018). "Key genomic mutation genes, including BRAF (35–60%) and NRAS (15–20%), have been identified, which has led to the development of targeted therapeutic treatments for advanced melanoma." (PMID 30400954, 2018).
melanoma (continued). "It will be interesting to observe the metabolic characteristics of melanoma cells after a treatment combination of metformin and BRAF inhibitors to better understand active mechanisms." (PMID 30186236, 2018). "Other authors observed increased MCL1 expression induced by oncogenic BRAF in melanoma, thereby inducing a more aggressive phenotype." (PMID 30197759, 2018). "The development of small‐molecule BRAF inhibitors and the BRAF‐MEK inhibitor combination has revolutionized the treatment for BRAF‐mutant melanoma." (PMID 29112787, 2018). "In this report, we explored the precise contribution of PI3K/AKT activity in melanoma responses to combination BRAF and MEK inhibitor treatment." (PMID 30237495, 2018). "The procedure can be used to identify a broad range of mutations, including KRAS, BRAF, and EGFR mutations, in patients with colon carcinoma, breast cancer, melanoma, and lung cancer." (PMID 29728089, 2018). "We also compared the expression of ABCB5 in the three parent cells that have BRAF mutation with that of another melanoma cell line, SK-MEL-2, which has wild-type BRAF expression." (PMID 29929490, 2018). "For example, the combination of vemurafenib, which targets BRAF, and cobimetinib, which targets MAP2K1, was approved by the FDA in 2015 for use in treating BRAF mutated melanoma." (PMID 29560824, 2018). "TNFR1 and TNFR2 were co-expressed by 48% of BRAF-V600E-mutant melanoma cell lines and primary melanomas." (PMID 30400822, 2018). "In fact, we found that human BRAF V600E mutant melanoma A375 cells display very little motility on fibronectin-coated glass." (PMID 29379163, 2018). "Previous reports have considered the activity of 17-AAG on the RAF kinases CRAF, and BRAF, in melanoma cells." (PMID 29481571, 2018). "Similar changes in the tumor immune microenvironment have been shown in melanoma patients after 2 weeks of BRAF inhibitor therapy prior to clinical progression." (PMID 29996921, 2018). "One important mediator of adaptive resistance in mutant BRAF melanoma cells is the lineage-specific transcription factor, FOXD3, which undergoes rapid transcriptional induction upon inhibition of ERK1/2 signaling and activates the ERBB3/PI3K/AKT pathway." (PMID 29295999, 2018). "While the human CDKN2A gene is mutated or deleted, which frequently occurred in some malignancies such as melanoma, tumor cells would overcome BRAF V600E-induced senescence and become malignant." (PMID 30111351, 2018). "In this report, we show that RIP1 protects human melanoma cells from apoptosis induced by BRAF/MEK inhibitors, and that this is mediated by activation of NF-κB." (PMID 29880840, 2018). "The BRAF melanoma model was used to understand the function of genes known to be overexpressed or amplified in human melanoma." (PMID 29443947, 2018). "For example, when domain experts who have extensive knowledge on melanoma annotate a text and see V600E, melanoma (disease), and BRAF (gene) in the text of an article, they can easily map V600E to the disease name and gene name." (PMID 29368597, 2018). "As anticipated, USP28-depleted melanoma cell lines were more resistant to BRAF inhibitor treatment and then their wild-type counterparts, as demonstrated by a rightward shift in the dose–response curve." (PMID 29880484, 2018). "Patient 2 is a 52-year old male who was originally diagnosed in 2011 with a localized BRAF V600E- melanoma of the left flank, and was treated with wide local excision (Breslow thickness: 2.8 mm) and adjuvant interferon alpha." (PMID 30305172, 2018). "We selected Gamitrinib, a mitochondriotoxic small molecule, that selectively blocks mitochondrial HSP90 and exhibits broad anti-cancer activity including efficacy in BRAF-mutant melanoma, but limited activity in NRAS-mutant cells as a single agent." (PMID 29695835, 2018).